ISOC2 (isochorismatase domain containing 2)
Synonyms: FLJ23469
Tractability: PROTAC: ubiquitination databases record sites on it; its protein half-life has been measured.
Gene: Protein-coding gene on chromosome 19 (55,452,975 to 55,462,343, reverse strand). Ensembl gene ENSG00000063241.
Subcellular location: Cytoplasm; Nucleus
Subcellular location (Human Protein Atlas): Mitochondria; Cytosol
Gene Ontology:
Molecular function: protein binding
Biological process: protein destabilization
Cellular component: cytoplasm; cytosol; mitochondrion; nucleus
Genetic constraint (gnomAD): Loss-of-function variants: 16 observed, 19.7 expected, observed/expected ratio (o/e) 0.81, 90% interval 0.55 to 1.23. The upper end of that interval is the gene's LOEUF score, 1.23, which puts it in group 5 of 6, group 1 being the genes least tolerant of losing a copy. Missense variants: 284 observed, 267.42 expected, observed/expected ratio (o/e) 1.06, 90% interval 0.96 to 1.17. Synonymous variants: 106 observed, 115.73 expected, observed/expected ratio (o/e) 0.92, 90% interval 0.78 to 1.08.
Homologues: Orthologues: chimpanzee ISOC2 (98% identical), macaque ISOC2 (96% identical), guinea pig ISOC2 (85% identical), mouse Isoc2a (83% identical), pig ISOC2 (83% identical), rat Isoc2a (83% identical), dog ISOC2 (81% identical), mouse Isoc2b (76% identical), rat Isoc2b (75% identical), tropical clawed frog isoc2 (65% identical), zebrafish isoc2 (58% identical), Caenorhabditis elegans marb-1 (50% identical). Paralogues in human: ISOC1 (49% identical).
Diseases named in the same sentence as ISOC2 in open-access papers:
ISOC2 is named in the same sentence as 3 diseases in open-access papers, as found by Europe PMC text mining. Sharing a sentence is not in itself a finding about the gene and the disease. The quoted sentences say what the papers report.
craniosynostosis (1 paper, 2023). Craniosynostosis is defined as the premature fusion of one or more cranial sutures leading to secondary distortion of skull shape resulting in skull deformities with a variable presentation. "However, also in this case interesting examples of co-occurrences may be found, often involving genes known to be associated with Psoriasis, such as QTRT1, as well as genes related to other diseases, e.g. ERF, implied in complex craniosynostosis, and ISOC2, biomarker of Osteoarthrosis Deformans." (PMID 37021928, 2023).
tumor (2 papers, 2015 to 2025). "In accordance, isochorismatase domain containing 2 is a protein that has been associated with the inhibition of tumor-suppressing proteins, thus contributing to increased rates of cell growth and differentiation." (PMID 41302034, 2025).
ISOC2 also shares sentences with these, for which no sentence is quoted: psoriasis (1 paper).